CXCL8 (C-X-C motif chemokine ligand 8)
Diseases named in the same sentence as CXCL8 in open-access papers (continued):
Sharing a sentence is not in itself a finding about the gene and the disease.
epidermolysis bullosa simplex (2 papers, 2013 to 2021). Epidermolysis bullosa simplex (EBS) is a group of hereditary epidermolysis bullosa (HEB) disorders characterized by skin fragility resulting in intraepidermal blisters and erosions that occur either spontaneously or after physical trauma. "To evaluate these data in vivo we analysed the blister fluids of epidermolysis bullosa simplex patients vs. healthy controls and identified matrix metalloproteinase-9 and the chemokine CXCL8/IL-8 as potential therapeutic targets." (PMID 23894602, 2013).
Ewing sarcoma (2 papers, 2011 to 2025). A small round cell tumor that lacks morphologic, immunohistochemical, and electron microscopic evidence of neuroectodermal differentiation. "The survival analysis showed that high expression of IL8, also known as CXCL8, associates with unfavourable survival in classical Ewing sarcoma of bone." (PMID 22084725, 2011).
Flavivirus Infections (2 papers, 2019 to 2022). Infections with viruses of the genus FLAVIVIRUS, family FLAVIVIRIDAE. "In order to investigate the response of the respiratory epithelium upon flavivirus infection, we measured the expression levels of type I and type III IFNs and the pro-inflammatory cytokines IL-6, IL-8/CXCL8, and IP-10/CXCL10." (PMID 31057517, 2019). "Additionally, excluding for JEV, flavivirus infection did not induce a significant IFN response in comparison to mock controls and led to the activation of NECs, indicated by an increase in the expression of the inflammatory mediators IL-8/CXCL8 and IP-10/CXCL10." (PMID 31057517, 2019).
HIV encephalitis (2 papers, 2010 to 2021). "Increased expression of CXCL10 and CXCL8 in astrocytes was also reported in brains of individuals with HIV encephalitis." (PMID 20877724, 2010).
idiopathic pulmonary arterial hypertension (2 papers, 2022 to 2024). A sporadic form of pulmonary arterial hypertension (PAH) characterized by elevated pulmonary arterial resistance leading to right heart failure. "Compared with the normal controls, the expression of C-X-C motif chemokine ligand 8 (CXCL8) in idiopathic pulmonary arterial hypertension (IPAH) is increased and was associated with an increased risk of IPAH and unfavorable clinical features." (PMID 35958401, 2022).
measles (2 papers, 2016 to 2023). A highly contagious viral infection caused by the measles virus. "Further in vivo evidence of the innate response during measles, are increased plasma levels of NFκB-induced proteins IL-6 and IL-8/CXCL8 and inflammasome products IL-1β and IL-18." (PMID 27754341, 2016).
obstructive uropathies (2 papers, 2013 to 2014). "In pediatric patients with CAKUT, the chemokine CCL2/MCP-1 has been associated with urinary tract obstruction in UPJO, whereas high urinary levels of CXCL8/IL-8 were found in VUR." (PMID 24692841, 2014). "Based on these results, it should be further investigated if urinary measurements of CCL2/MCP-1 would help detecting obstructive uropathies and if high urine levels of CXCL8/IL-8 would indicate the presence of renal scarring in VUR." (PMID 24692841, 2014). "The chemokine CCL2/MCP-1 and the cytokine TGF-β have been frequently associated with urinary tract obstruction in patients with UPJO, whereas high urinary levels of IL-6 and of CXCL8/IL-8 were found in many patients with VUR and correlated to renal scarring and to renal function deterioration." (PMID 24066006, 2013).
occupational asthma (2 papers, 2016 to 2025). Asthma attacks caused, triggered, or exacerbated by OCCUPATIONAL EXPOSURE. "Styrene has previously been linked to airway inflammation present in people with occupational asthma and has also been shown to induce monocyte chemotactic protein-1 (MCP-1) and CXCL8 release from an alveolar epithelial cell line." (PMID 27184092, 2016).
pancreas diseases (2 papers, 2016 to 2021). "In the alcohol group, CXCL8 concentrations were increased in patients with liver and pancreas diseases and there was a significant correlation to aspartate transaminase (r = +0.456, p < 0.001) and gamma-glutamyltransferase (r = +0.647, p < 0.001)." (PMID 28149283, 2016).
penile cancer (2 papers, 2024 to 2025). A primary or metastatic malignant neoplasm that affects the penis. "Beyond that, in HPV16-associated penile carcinoma, we have recently shown that elevated p63 levels are associated with increased production of the neutrophil-recruiting chemokine CXCL8." (PMID 38510961, 2024). "For example, HPV + tumors in penile cancer recruit CD15 + myeloid cells through CXCL-8, forming an immunosuppressive microenvironment, which is associated with a poor prognosis." (PMID 41474538, 2025).
pertussis (2 papers, 2016 to 2025). A contagious bacterial respiratory infection caused by Bordetella pertussis. "The fact that neutrophils are characterized by the presence of binding sites with a high affinity for CXCL8, together with the observation that Pertussis toxin is able to block the effects of CXCL8, indicated that chemokine receptors are GPCRs." (PMID 27891127, 2016).
pneumococcal infection (2 papers, 2015 to 2016). Infections with bacteria of the species streptococcus pneumoniae. "Cytokine networks involved in pneumococcal infections are incompletely understood but IL-1β has been shown to regulate CXCL8 release from epithelial cells in reponse to S. pneumoniae and would be an interesting target for future study." (PMID 27430279, 2016).
pneumonic pasteurellosis (2 papers, 2014 to 2025). Bovine respiratory disease found in animals that have been shipped or exposed to cattle recently transported. "CXCL-8 (IL-8), is a key chemokine involved in neutrophil recruitment, that triggers tissue injury during pneumonic pasteurellosis, and is overexpressed not only in M. haemolytica infections, but also in response to BRSV infection." (PMID 40703922, 2025).
pyometra (2 papers, 2015 to 2016). "COX-2 interacts directly with CXCL8/IL-8 and CXCL14, chemokines that were also overexpressed in pyometra." (PMID 26222498, 2015).
secretory otitis media (2 papers, 2024). "Moreover, studies of Swedish children with acute or secretory otitis media have shown higher levels of IL-1β and CXCL8 in middle ear fluids if culturable, living bacteria were present, as compared with children without culturable bacteria." (PMID 38271409, 2024).
severe combined immunodeficiency (2 papers, 2010 to 2013). Severe combined immunodeficiency (SCID) comprises a group of rare monogenic primary immunodeficiency disorders characterized by a lack of functional peripheral T lymphocytes resulting in early-onset severe respiratory infections and failure to thrive. "Adoptive transfer of those cells into severe combined immunodeficiency (SCID) or naïve BALB/c mice induced the development of airway neutrophilia and AHR accompanied by increased expression of IL-17 and neutrophil chemoattractants such as CXCL 5, CXCL8, and G-CSF, after OVA challenge." (PMID 24454477, 2013).
Subdural Effusion (2 papers, 2017 to 2022). Leakage and accumulation of CEREBROSPINAL FLUID in the subdural space which may be associated with an infectious process; CRANIOCEREBRAL TRAUMA; BRAIN NEOPLASMS; INTRACRANIAL HYPOTENSION; and other conditions. "It has been proposed that CXCL8 inducing a neutrophil respiratory burst is the crucial impact when subdural effusion develops into CSDH, and that an increased concentration of CXCL8 may increase the risk of RrR." (PMID 29107999, 2017).
trigeminal neuralgia (2 papers, 2021 to 2022). Trigeminal neuralgia is a nerve disorder that causes a stabbing or electric-shock-like pain in parts of the face. "In the present study patients with trigeminal neuralgia showed lower levels of growth factor levels such as Ang-2, bFGF, HGF, SCF, TGF-α, and VEGF and higher cytokine levels of IL-1β, TNF-α, CCL2, IL-17A, IL-6, and CXCL8 in comparison with normal individuals." (PMID 34067581, 2021).
type 2 diabetic nephropathy (2 papers, 2022 to 2025). "Moreover, urinary CXCL8 levels were markedly increased in type 2 diabetic nephropathy (T2DN) patients." (PMID 40650083, 2025).
ventricular fibrillation (2 papers, 2016 to 2023). A disorder characterized by an electrocardiographic finding of a rapid grossly irregular ventricular rhythm with marked variability in QRS cycle length, morphology, and amplitude. "Elmas and colleagues studied the levels of matrix-degrading metalloproteinases, their inhibitors (TIMPs), and CXCL8, the predominant chemokine interacting with them, in patients with MI complicated or not by ventricular fibrillation (VF)." (PMID 27242392, 2016).
viral myocarditis (2 papers, 2021 to 2024). Myocarditis that is caused by an infection with a viral agent. "In the acute phase of viral myocarditis, CVB3 internalization leads to increased secretion of IL-6, IL-1β, TNF-α, and IL-8/C-X-C motif chemokine ligand 8, and infected neutrophils released MPO and triggered NETosis in the presence of TNF-α." (PMID 33680285, 2021).
Acanthamoeba keratitis (1 paper, 2022). Keratitis due to infection by acanthamoeba; it is usually associated with soft contact lens wear, particularly overnight wear. "SNPs in IL1B (rs16944), CXCL8 (rs2227307, rs2227543, and rs1126647), and IL22 (rs1179251) have been associated with decreased risk of severe inflammatory complications during Acanthamoeba keratitis." (PMID 36422638, 2022).
acne inversa (1 paper, 2018). "Our immunohistochemical analysis of acne inversa patients showed no significant expression of CXCL8 in macrophages but particularly in keratinocytes and endothelial cells, with a high expression of CXCL8 after 2 days." (PMID 29338773, 2018).
alcohol (1 paper, 2016). "However, alcohol-induced diseases in accessory organs influenced strongly the plasma expression of CXCL8." (PMID 28149283, 2016).
amyloid (1 paper, 2017). "In addition, the co-presence of CXCL4 and CXCL8, in turn, attenuates the CXCL8-mediated rise in intracellular calcium in the amyloid progenitor cell line and enhances CXCL8-induced migration of bone-marrow-derived pro-B-cells (Baf/3)." (PMID 28974038, 2017).
anaerobic bacterial infections (1 paper, 2017). "In the context of anaerobic bacterial infections, mRNA expression of IL1α, CXCL8, TNFα and human beta defensin (hBD)-2 were stimulated in keratinocytes by Propionibacterium acnes, an anaerobic bacterium." (PMID 28959685, 2017).
burn (1 paper, 2024). A traumatic injury involving interruption of tissue cohesiveness that results from exposure to caustic chemicals, extreme heat, extreme cold or excessive radiation. "Burn patients showed a decreased enrichment of H3K9me2 in CXCL8, IL-17, and TNFA promoters, whereas IL-6, FOS, and IL-1B promoters displayed an H3S28p enrichment diminution during the first 10 days post-burn." (PMID 39768289, 2024).
cerebral cavernous malformation (1 paper, 2025). A disorder characterized by malformations in the structure of the capillaries in the brain. "There is currently no direct research on CXCL8 and cerebral cavernous malformation (CCM), exploring the pathways involving CXCL8 reveals some associations." (PMID 40519934, 2025).
cerebrovascular disorder (1 paper, 2023). A disorder resulting from inadequate blood flow in the vessels that supply the brain. "Few studies also explored CXCL8 signaling in cerebrovascular disorders." (PMID 38002055, 2023).
chronic cervicitis (1 paper, 2024). Chronic inflammation of the cervix. "We used a set of patient-derived precancerous (n = 32) and noncancerous (chronic cervicitis; n = 10) tissue samples to investigate the gene expression of several OIS (LMNB1, CDKN2A, CDKN2B, and CDKN1A), and SASP (IL1A, CCL2, TGFB1, CXCL8, and MMP9) biomarkers using qRT-PCR." (PMID 39727946, 2024).
cocaine addiction (1 paper, 2025). "The strong positive correlations observed between genes like CCL2, CD44, and CXCL8 further suggest coordinated regulation of immune processes in cocaine addiction, which may be modulated by exercise." (PMID 41465087, 2025).
diabetic eye disease (1 paper, 2024). A group of disorders affecting the eye in patients with diabetes mellitus. "Our study suggests that CCL2 and CXCL8 may play key roles in pathogenesis of diabetic eye disease." (PMID 38790059, 2024). "Network meta-analysis revealed that CCL8, CCL2, CXCL8 and CXCL10 may be involved in key pathophysiological process of diabetic eye disease." (PMID 38790059, 2024). "Specifically, this network meta-analysis indicated that CC chemokines (CCL8 and CCL2) and CXC chemokines (CXCL8 and CXCL10) may discriminate between those with and without diabetic eye disease." (PMID 38790059, 2024).
epilepsy syndrome (1 paper, 2022). A syndrome that has a characteristic cluster of clinical features and/or lectroencephalographic (EEG) findings that reflect underlying epileptic activity. "Particularly, a recent systematic review showed increased levels of IL-1ra, IL-1, IL-6, and CXCL8/IL-8 in several different epilepsy syndromes independently of the underlying etiology." (PMID 35327518, 2022).
female infertility (1 paper, 2020). Diminished or absent ability of a female to achieve conception. "489TT/HHV-6A positive women also showed higher levels of IL-1β, IL-1α, and IL-8 (CXCL8) suggesting that the 489TT gain-of-function variant not only favors virus entry but also triggers a wide inflammatory response that might contribute to female infertility." (PMID 32153407, 2020).
gastroesophageal junction adenocarcinoma (1 paper, 2022). A carcinoma that arises from glandular epithelial cells of the esophagogastric junction. "The model confirmed that all EACs must originate from BE and pinpointed a CXCL8/IL8↔neutrophil immune microenvironment as a driver of cellular transformation in EACs and gastroesophageal junction adenocarcinomas." (PMID 36134663, 2022).
Gliosis (1 paper, 2012). Gliosis is the focal proliferation of glial cells in the central nervous system. "Since mIns, as tCr, is considered a marker of glia cells, it is worth pointing out that no firm association between one-year change in mIns concentrations to levels of IL-1β and CXCL8 was observed, which one could argue should be demonstrated if both tCr and mIns represented gliosis." (PMID 23028598, 2012).
hip osteoarthritis (1 paper, 2025). "Further ligand-receptor interaction analyses showed that the VEGFA, VEGFB and CXCL8 associated interaction pairs were significant in the crosstalk between neutrophil and endothelium in hip osteoarthritis (HOA) group which may enhance the angiogenesis." (PMID 40169566, 2025).
histoplasmosis (1 paper, 2021). A disease caused by the fungus Histoplasma capsulatum. "Our study shows, for the first time, CXCL8 in human histoplasmosis." (PMID 34829225, 2021).
Hookworm infection (1 paper, 2019). "Hookworm infection was associated with elevated placental IL-1, CXCL8 and IFN-γ." (PMID 31188820, 2019). "In this analysis, we also found that hookworm infection among pregnant women was associated with elevated Th1 (IL-1β and IFN-γ) cytokines, as well as IL-5 and CXCL8 in blood collected from the maternal-fetal interface." (PMID 31188820, 2019).
Hypofibrinogenemia (1 paper, 2020). Decreased concentration of fibrinogen in the blood. "The correlation network analyses between the molecules evaluated in the present study show that, in the group of patients with hypofibrinogenemia, it was possible to observe a predominance of a chemoattractive profile, with correlations between chemokines CXCL-8, CXCL-9, CCL-2, and CXCL-10." (PMID 32973773, 2020).
idiopathic interstitial pneumonia (1 paper, 2024). A class of diffuse lung diseases that typically affect the pulmonary interstitium, although some also have a component affecting the airways (for instance, Cryptogenic organizing pneumonitis). "Notably, various cell types, including type II pulmonary epithelial cells, alveolar and interstitial macrophages from patients with idiopathic interstitial pneumonia (IIP), and interstitial pneumonia with collagen vascular disease (IP-CVD), express CXCL8." (PMID 39768150, 2024).
Klebsiella Infections (1 paper, 2013). Infections with bacteria of the genus KLEBSIELLA. "CXCL8 (interleukin; (IL-8)), the prototypical ELR-CXC chemokine, is frequently detected in microbial infections, including Klebsiella infections." (PMID 23586055, 2013).
Klebsiella pneumonia (1 paper, 2014). An pneumonia caused by infection with Klebsiella. "It has been reported that stimulation of A549 cells with LPS, PGN or Klebsiella pneumonia together with recombinant sCD14 increases the release of chemokines, such as CXCL8 compared with stimulation with LPS, PGN, and Klebsiella pneumonia alone." (PMID 26557246, 2014).
lymphadenitis (1 paper, 2023). Acute or chronic inflammation of one or more lymph nodes. "CXCL9/MIG, CCL20, CCL23, CXCL10/IP-10, CXCL1, CXCL2, and CXCL8 significantly declined in our cohort of EPTB (48 TB pleuritis and 57 TB lymphadenitis) patients at both time points." (PMID 36635313, 2023).
Majeed syndrome (1 paper, 2021). Majeed syndrome is a rare genetic multisystemic disorder characterized by the triad of chronic recurrent multifocal osteomyelitis, congenital dyserythropoietic anemia, and variable transient inflammatory dermatosis. "Yet, only the cells from Majeed syndrome patients (versus NOMID or healthy controls) showed increased expression of osteoclastogenic mediators including IL-8, IL-6, TNF, CCL2, MIP1α, MIP-1β, CXCL8/IL-8 and CXCL1 in M2-like macrophages stimulated with LPS." (PMID 33670882, 2021).
neurosarcoidosis (1 paper, 2024). A sarcoidosis that involves the nervous system. "IL-6, BAFF, CXCL9, CXCL10, CXCL13, GM-CSF, IFN-gamma, and TNF-alpha levels were significantly elevated in CSF from neurosarcoidosis patients compared to controls (p<0.0001), along with IL-2 (p=0.0002), IL-8/CXCL8 (p=0.0008), IL-10 (p=0.0005), and IL-13 (p=0.0018)." (PMID 39398844, 2024).
oral epithelial dysplasia (1 paper, 2020). "Data from immunochemistry staining demonstrated that expression of CXCL8 was the highest in OSCC, second is oral epithelial dysplasia expression, and expression of CXCL8 was hardly detected in normal oral epithelial cells." (PMID 32588946, 2020).
ovarian mucinous adenocarcinoma (1 paper, 2021). An invasive adenocarcinoma that arises from the ovary and is characterized by the presence of malignant epithelial cells that contain intracytoplasmic mucin. "The research of Lu dataset showed that CXCL8 was elevated in ovarian mucinous adenocarcinoma compared with that in normal ovarian tissue." (PMID 33763130, 2021).
Pasteurella multocida infection (1 paper, 2024). "This new information may be useful in the development of measures to prevent the severe consequences of Pasteurella multocida infection and provide a basis for using PMT or CXCL8 to modulate the host immune response." (PMID 38791369, 2024).
Renal atrophy (1 paper, 2023). Atrophy of the kidney. "Specifically, previous studies identified CXCL8 as a DEG in IF/TA patients and Chi3l1 was upregulated in a mouse model of renal atrophy." (PMID 37623492, 2023).
status epilepticus (1 paper, 2023). Status epilepticus is defined as a continuous seizure lasting more than 30 min, or two or more seizures without full recovery of consciousness between any of them. "The last of these studies in 2023, demonstrated a significant increase in the serum and CSF of IL-6 along with TNF-α, CXCL8/IL-8, CCL2, MIP-1α, and IL-12p70 pro-inflammatory cytokines/chemokines in patients with status epilepticus (SE) compared with patients without SE." (PMID 37841263, 2023).
Stillbirth (1 paper, 2019). Death of the fetus in utero after at least 22 weeks of gestation. "The CXCL8 and PF4 are located within regions associated with calving-to-conception interval or calving-to-first-estrous interval, while S100A8 is within a stillbirth QTL region." (PMID 31374089, 2019).